INS (insulin)
Diseases named in the same sentence as INS in open-access papers (continued):
Sharing a sentence is not in itself a finding about the gene and the disease.
diabetes (continued). "The genetic factors influencing insulin action help explain the correlation between offspring birth weight, adult cardiovascular disease, and diabetes risk." (PMID 39770898, 2024). "Surrogate measures are used in a wide range of epidemiological studies wherein associations between insulin secretion and conditions related to diabetes are investigated." (PMID 39013634, 2024). "Diabetes mellitus is a group of multietiological metabolic diseases characterized by chronic hyperglycemia due to deficiencies in insulin secretion and/or utilization." (PMID 38884020, 2024). "Insulin and insulin resistance can affect brain myelin content, which is associated with cognitive decline in diabetes." (PMID 38380813, 2024). "Diabetes is a group of metabolic disorders caused by absolute or relative insufficiency of insulin secretion or issues with insulin utilization, with hyperglycemia as the primary indicator." (PMID 39582669, 2024). "Diabetes mellitus (DM) is characterized by deficient insulin secretion, action, or both, culminating in hyperglycemia." (PMID 38792681, 2024). "Lifestyle approaches aiming to prevent diabetes through moderate weight loss, a healthy diet, and increased physical activity have proven highly successful due to improvements in insulin sensitivity and insulin secretion." (PMID 38928106, 2024). "Diabetes mellitus, being a condition caused by either insufficient insulin or insulin resistance, falls under the field of endocrinology." (PMID 39583130, 2024). "Lastly, younger age, longer diabetes duration, and higher daily insulin requirements were consistently associated with poorer chronic control, as indicated by both glycated hemoglobin and sensor data at 14 and 90 days." (PMID 37930420, 2024). "Diabetes is widely assumed to be caused by a reduction in the insulin sensitivity of various tissues and organs throughout the body, or by a decrease in endogenous insulin secretion." (PMID 38643133, 2024). "Ultimately, the continued refinement of insulin therapies is crucial in tackling the global rise in diabetes and its associated complications, offering hope for a future where managing diabetes is easier, safer, and more effective." (PMID 39734941, 2024). "Our study underscores the significance of insulin therapy in mitigating sarcopenia risk among Type 2 Diabetes Mellitus (T2DM) patients." (PMID 39058051, 2024). "Some flavonoids can help manage diabetes by improving insulin sensitivity and glucose metabolism, potentially reducing the risk of diabetes-related complications." (PMID 38398660, 2024). "One main characteristic of diabetes is chronic hyperglycemia caused by a defect in insulin production and secretion, insulin action, or both." (PMID 38396989, 2024). "Hyperglycemia, a result of insufficient insulin synthesis or activity, is a hallmark of diabetes mellitus, an inflammatory illness." (PMID 38337597, 2024). "Diabetes is a serious chronic metabolic disease caused by hyperglycemia and a relative or absolute deficiency in insulin secretion." (PMID 39596482, 2024). "Considering the phenotypical spectrum of INSR gene variants and the consistently increased insulin levels, our patient will be closely monitored for the potential development of type 2 diabetes mellitus." (PMID 39659391, 2024). "Managing hyperglycemia in these patients is challenging and often requires a combination of oral antidiabetic agents and large doses of insulin, resulting in early onset complications associated with diabetes." (PMID 38633761, 2024). "More than 90% of patients with diabetes worldwide are type 2 diabetes (T2D), which is caused by insulin resistance or impaired producing insulin by pancreatic β cells." (PMID 38297222, 2024). "Other evidence suggests that dietary magnesium has beneficial effects, including regulating systemic inflammation and hypertension, regulating lipids, glucose and insulin metabolism, improving insulin sensitivity, and reducing the risk of diabetes." (PMID 38366015, 2024).
diabetes (continued). "Taken together with the present results, activation of vagal nerves is a potentially practical and promising therapeutic option for insulin-deficient diabetes." (PMID 37945752, 2024). "An additional diabetes-related safety concern is the potential for unregulated insulin secretion by the transplanted cells, which can cause hypoglycemia, resulting in loss of consciousness, seizures and life-threatening consequences." (PMID 39696686, 2024). "Obesity is often associated with reduced glucose metabolism and insulin sensitivity, which increase the risk of diabetes." (PMID 39631563, 2024). "Diabetes mellitus is a metabolic disease resulting in chronic hyperglycemia caused by problems with insulin secretion, insulin action, or both." (PMID 39274877, 2024). "People with type 2 diabetes who received insulin treatment were at a higher risk for developing diabetes distress than those who had only oral medication." (PMID 38585475, 2024). "Commonly, they present typical symptoms of diabetes mellitus such as polyuria, polydipsia, polyphagia, weight loss, and the need for large doses of insulin for management." (PMID 39518747, 2024). "Currently, the treatment and management of diabetes are suboptimal due to the risk of iatrogenic hypoglycemic seizures that can occur due to hyperglycemic corrections with short-acting insulin." (PMID 38975425, 2024). "Diabetes is a systemic disease that manifests due to either a deficiency in insulin production or a failure in insulin action, leading to widespread pathological changes across multiple organ systems." (PMID 38891952, 2024). "Diabetes is an endocrine and metabolic disorder characterized by defects in insulin secretion and/or action and chronic hyperglycemia, caused by various factors." (PMID 39229261, 2024). "The association between insulin therapy and the development of other diabetes complications warrants further investigation." (PMID 39295783, 2024). "Use of sulfonylureas and insulin carries a greater risk of hypoglycemia than diabetes medications acting via alternative mechanisms, including GLP-1 RAs such as liraglutide and DPP4 inhibitors such as sitagliptin." (PMID 39546502, 2024). "Either insufficient insulin production by the pancreas or ineffective insulin uptake by the body causes diabetes, a chronic illness." (PMID 38814943, 2024). "Excessive oxidative stress in the pancreas interferes with insulin synthesis and causes diabetes mellitus with hyperglycemia, which leads to many complications in the body." (PMID 38881175, 2024). "The HHEX rs1111875 and rs5015480, have been associated with diabetes risk across diverse populations, primarily due to their role in reducing β-cell response and insulin secretion." (PMID 39659616, 2024). "Diabetes results in hyperglycaemia; in around 10% of diabetes cases this is caused by poor insulin production by the pancreas (Type 1) and in around 90% of cases result from insulin resistance or dysfunction (Type 2)." (PMID 39238333, 2024). "Patients with diabetes typically exhibit insulin resistance (IR), the pathological foundation of diabetes, which is a complex pathological state caused by a reduced insulin sensitivity in insulin target organs due to various factors." (PMID 39517172, 2024). "It is worth noting that many past studies did not evaluate the risk specifically associated with the use of insulin, but instead focused on insulin-dependent diabetes mellitus." (PMID 39407755, 2024). "According to our results, the intrinsic emotional burden of living with diabetes and the perception of receiving inadequate insulin treatment were strong independent risk factors for both anxiety and depression irrespective of sex." (PMID 38743078, 2024). "Type 1 diabetes mellitus is caused by the immune destruction of insulin-producing pancreatic β-cells." (PMID 38542165, 2024).
diabetes (continued). "Abnormal glucose metabolism is a metabolic disorder that causes diabetes, a disease that requires the close monitoring of blood glucose and clinical treatment by the daily adjustment of insulin doses while also making an appropriate dietary choice." (PMID 38667679, 2024). "Among these factors, BMI, ALB, Hb, TG, HDL‐C, HbA1c, CRP >10 mg/L, age, duration of diabetes, Wagner grades 3–5, and using insulin were significantly associated with malnutrition in diabetic patients." (PMID 39364802, 2024). "It is well-established that obesity-related diabetes is primarily linked to IR and compromised insulin secretion." (PMID 39588337, 2024). "Heterozygous mutations that perturb proinsulin folding act as dominant-negative alleles, leading to insulin insufficiency, β cell loss, and autosomal-dominant diabetes referred to as mutant INS gene–induced diabetes of youth." (PMID 38935435, 2024). "The loss of β‐cells through apoptosis reduces insulin production, which contributes to the onset and progression of diabetes." (PMID 39055210, 2024). "Stimulating insulin secretion, improving pancreatic β-cell functionality, enhancing glucose uptake, and increasing insulin signaling pathway are some of the putative mechanisms by which cinnamic acids and their derivatives reduce the risk of diabetes." (PMID 39394552, 2024). "STZ-induced diabetes is associated with impairment of the amylase-release mechanism and/or its synthesis, and insulin treatment can reverse pancreatic insufficiency in diabetic animals." (PMID 38675446, 2024). "Adherence to diabetes medications (oral hypoglycemic agents or insulin) and risk of CVD event in the Pathways Heart Study." (PMID 39298390, 2024). "In the setting of diabetes, insulin administration often causes local dermal fibrosis, leading to a range of clinical sequelae including impeded insulin absorption." (PMID 38464040, 2024). "The main mechanism is to increase the risk of diabetes by impairing the insulin secretion function of islet β-cells and changing the expression of insulin-related genes." (PMID 38921478, 2024). "Elevated blood glucose levels are the hallmark of diabetes mellitus (DM), a metabolic condition that can develop due to insufficiency in insulin synthesis or its action, or both." (PMID 38998954, 2024). "Diabetes mellitus (DM) is a group of metabolic diseases characterized by hyperglycemia caused by defects in either insulin secretion or action, or both." (PMID 39247917, 2024). "Diabetes is a chronic metabolic disorder characterized by insufficient insulin secretion and/or insulin resistance caused by environmental and genetic factors." (PMID 39713052, 2024). "This lipotoxicity hampers the secretion of insulin by pancreatic β-cells, eventually causing β-cell exhaustion and the development of diabetes." (PMID 39086906, 2024). "The patient carrying the first variant developed impaired fasting glucose (IFG) at the age of 31 years and underwent dietary treatment, while the patient carrying the second variant developed diabetes at the age of 6 months, requiring insulin therapy." (PMID 39201476, 2024). "Diabetes-induced peripheral arterial disease is responsible for causing critical limb ischemia, insulin resistance, and hyperglycemia, which bring about metabolic changes that are damaging to muscles, thereby retarding their healing." (PMID 39371721, 2024). "Diabetes is a chronic disease caused by insufficient production/secretion of insulin by the pancreas or insulin resistance and is characterized by uncontrolled hyperglycemia and concomitant metabolic disturbances." (PMID 39139674, 2024). "In people with T2D, diabetes stigma is associated with female sex, higher body mass index, and use of insulin." (PMID 39105174, 2024). "Regarding nutrition, research has shown that caloric restriction leads to mutations in insulin signalling pathways, promoting improvements in sarcopenia, cardiovascular disease, diabetes, Alzheimer’s disease, and cancer." (PMID 39541406, 2024).
diabetes (continued). "Diabetes is a pandemic disease that causes the loss of control of glucose regulation in the organism, in consequence of dysfunction of insulin production or functionality." (PMID 39739113, 2024). "Loss of glucose-stimulated [Ca2+]i dynamics coordination linked to uncoordinated insulin secretion has been described as an early sign of diabetes associated with loss of insulin pulsatility and deteriorated insulin sensitivity." (PMID 38814444, 2024). "Chronic hyperglycemia is a hallmark of diabetes mellitus (DM), a long-term metabolic disease caused by deficiencies in either the production of insulin, the action of insulin, or both." (PMID 39766193, 2024). "In male mice, the larger Kv2.1 currents cause a reduced β cell firing frequency that translates to reduced second-phase insulin release and therefore increased susceptibility to diabetes." (PMID 38358819, 2024). "The current case report provides insights into the management of individuals with diabetes caused by the heterozygous pathogenic variant R46Q in the insulin gene." (PMID 39027635, 2024). "In this study, K allele (diabetes risk allele) carriers showed higher fasting glucose, reduced insulin secretion and beta-cell function." (PMID 38267622, 2024). "Insulin-treated diabetes is more likely to be associated with NSCLC and well-differentiated tumors, particularly in those who are former or current smokers." (PMID 39044884, 2024). "Numerous studies have shown that MTOR is an important gene in the insulin signalling pathway and susceptibility to type 2 diabetes mellitus." (PMID 38932873, 2024). "Diabetes is a metabolic condition characterized by chronic hyperglycemia, resulting from either an absolute or a relative deficiency of insulin, impaired insulin action, or both." (PMID 39895840, 2024). "This commonality explains why hypertension was a significant risk factor for diabetes in the regression model, with insulin resistance contributing to increased blood pressure." (PMID 38516406, 2024). "STZ causes the destruction of the pancreatic islet in diabetes mice, which is more similar to the insulin-dependent T1DM." (PMID 38715117, 2024). "Diabetes is a disease caused by insufficient production of insulin and/or inadequate utilization of insulin, which leads to elevated blood glucose levels." (PMID 39409382, 2024). "The abnormalities in carbohydrate, fat, and protein metabolism in diabetes are attributed to the deficient action of insulin on target tissues." (PMID 39415841, 2024). "LADA is characterized by the presence of diabetes-associated autoantibodies and a clear need for insulin therapy." (PMID 38999290, 2024). "Monogenic diabetes is a type of diabetes caused by changes in genes that affect how the body makes or responds to insulin." (PMID 39025920, 2024). "Historically identified as a member of the glycosyltransferase family, GALNT2 was found to modulate adipogenesis and insulin signaling in adipocytes, impacting metabolic processes associated with obesity and diabetes." (PMID 38596689, 2024). "Diabetes mellitus (DM) is a global health concern characterized by a deficiency in insulin production." (PMID 38891245, 2024). "Lung cancer (LC) is the second most common cancer and the leading cause of cancer deaths in the U.S. Insulin therapy, a key treatment for managing Type 2 Diabetes Mellitus (T2DM), is associated with increased LC risk." (PMID 39001440, 2024). "UC-MSC therapy can promote the regeneration and functional recovery of β-cells, attenuate the dedifferentiation of β-cells caused by the inflammatory microenvironment in diabetes, and improve the ability to secrete insulin." (PMID 39000700, 2024). "The comprehensive whole transcriptomic sequencing revealed novel non-coding RNA-mRNA regulatory networks associated with impaired insulin secretion and increased β-cell mass in obesity-related diabetes." (PMID 38557554, 2024).
diabetes (continued). "Diabetes is well-known as a metabolic disorder characterized by associated hyperglycemia with disrupted insulin production or activity." (PMID 38164482, 2024). "As one of the pathological factors of diabetes, IR was the cell abnormal response to insulin stimulation, which caused the body to produce much more insulin, compensatively." (PMID 38617433, 2024). "Regular consumption of fruits and vegetables has been associated with improved insulin sensitivity and lower inflammation levels, both of which are important for reducing diabetes risk." (PMID 39867544, 2024). "A comparison between normoglycemia, prediabetes, and diabetes groups indicates that higher serum zinc concentration is associated with lower insulin secretion and lower insulin resistance in prediabetic individuals." (PMID 39596259, 2024). "Diabetes mellitus (DM) is a chronic metabolic disease characterized by elevated blood glucose caused by deficiency or resistance to insulin." (PMID 38797859, 2024). "Naturally occurring hypercortisolism and hypothyroidism are endocrinopathies that reduce insulin sensitivity, potentially predisposing to the development of diabetes mellitus (DM) and leading to instability in diabetic control." (PMID 39535393, 2024). "Older patients with type 2 diabetes mellitus (T2D) have an increased risk of hypoglycaemic episodes when using sulphonylureas or insulin." (PMID 39049109, 2024). "In the case of vitamin D supplementation, the need for insulin was reduced and so was the risk of diabetes." (PMID 38612580, 2024). "Blunted first-phase insulin secretion and insulin deficiency are indicators of β cell dysfunction and diabetes manifestation." (PMID 39587340, 2024). "On the other hand, several studies are currently looking at the performance of GHSA, insulin, and other biomarkers associated with type 2 diabetes mellitus and its complications." (PMID 39091901, 2024). "Our study further identified risk factors—being a female, chronic heart failure and, diabetes requiring insulin—for RSV infection in this population." (PMID 39284784, 2024). "Insulin resistance and/or insulin secretion dysfunction are crucial causes of type 2 diabetes mellitus (T2DM)." (PMID 39076511, 2024). "The metabolic score for insulin resistance index (METS-IR) is a novel non insulin-based marker that indicates the risk for metabolic syndrome and type 2 diabetes mellitus (T2DM)." (PMID 38572476, 2024). "Hypercortisolism is characteristically associated with the development of obesity and reduced insulin sensitivity, favouring almost 30% of patients with impaired fasting glucose and reduced glucose tolerance until diabetes mellitus." (PMID 39200374, 2024). "In the presence of diabetes, this can lead to a heightened risk of hypoglycemia, especially if insulin or other glucose-lowering medications are being used." (PMID 38669382, 2024). "Diabetes mellitus (DM) is a metabolic disorder characterized by persistent hyperglycemia, caused by a deficiency in insulin production, action, or both mechanisms." (PMID 38337649, 2024). "Given the high oxidative stress levels typically present in diabetic patients, vitamin C supplementation can alleviate oxidative stress, improve insulin sensitivity, and reduce the incidence of cardiovascular complications associated with diabetes." (PMID 39149550, 2024). "Our Cox model allowed us to explore the risk for pancreatic cancer associated with use of GLP-1RA compared with basal insulin, with all other characteristics being equal, including history of pancreatitis, other glucose-lowering drugs, and length of diabetes." (PMID 38175642, 2024). "Diabetes mellitus (DM), caused by ineffectiveness or deficiency of the insulin hormone secreted by the beta islet cells of the pancreas, is affected by hereditary and environmental factors." (PMID 39051061, 2024).